BACE1 (beta-secretase 1)
Diseases named in the same sentence as BACE1 in open-access papers (continued):
Sharing a sentence is not in itself a finding about the gene and the disease.
Alzheimer disease (continued). "Additionally, miR‐186‐5p targets BACE1, the crucial enzyme in β‐amyloid formation, suggesting that this miRNA plays a key role in Alzheimer's disease." (PMID 40275616, 2025). "Therefore, inhibiting BACE1 activity is a critical therapeutic target in the treatment of Alzheimer’s disease." (PMID 40137277, 2025). "Among the resultinganalogs, compound 208, bearing a fluoromethyl group, demonstratedpotent BACE-1 inhibition, robust CNS exposure, significant Aβ-loweringeffects in both rodent and canine models, and evidence of amyloidplaque reduction in Alzheimer’s disease mouse models." (PMID 40852238, 2025). "For example, the design of a compound which processes the inhibitory activity of losartan (AT1 inhibitor) and Lanabecestat (a potent BACE1 inhibitor) could open new paths in the treatment of Alzheimer’s disease." (PMID 41009387, 2025). "Growing evidence indicates that increased serum BACE1 (sBACE1) activity might represent an early biomarker for Alzheimer’s disease." (PMID 39828771, 2025). "BACE1 and γ-secretase are potential targets for treating Alzheimer’s disease." (PMID 40429850, 2025). "For example, heterophyllin B exhibits neuroprotective effects in Alzheimer’s disease models but lacks direct evidence of modulating the BACE1 enzyme; polysaccharides show TLR4-mediated immune regulation, yet their synergistic interactions with cyclic peptides remain unstudied." (PMID 40942180, 2025). "More recently, a generative AI framework applied to BACE1 produced novel scaffolds with in silico-predicted potency against Alzheimer’s disease, representing the first AI-only de novo discovery of β-site amyloid precursor protein cleaving enzyme 1 (BACE1) inhibitors." (PMID 40725054, 2025). "Background/Objective: Alzheimer's disease (AD) is characterized by the accumulation of amyloid-β plaques, derived from the amyloid precursor protein through sequential cleavage by β-secretase 1 (BACE-1) and γ-secretase." (PMID 41599607, 2025). "The model effectively meets the criteria for Alzheimer’s disease (AD) formation, demonstrated by significant memory impairment, increased levels of brain lipid peroxidation biomarkers, elevated inflammatory cytokines, BACE1, and the presence of Aβ deposits." (PMID 40325262, 2025). "BACE1 is primarily known for its role in Alzheimer’s disease (AD)." (PMID 40601773, 2025). "BACE1 SUMOylation is a reciprocal regulator of its phosphorylation and ubiquitination, which may have implications for the regulation of BACE1 activity and Aβ accumulation in Alzheimer’s disease." (PMID 38347638, 2024). "Additionally, the aberrant expression of miR-107 can result in abnormal activity of BACE1 (beta-secretase 1) and contribute to the pathogenesis of Alzheimer’s disease." (PMID 38605642, 2024). "In addition, ATRA downregulates BACE1 expression in the brains of Tg2576 mice which are one of the most well characterized, and widely used, mouse models of Alzheimer’s disease." (PMID 38572181, 2024). "Barros-Viegas A.T., Carmona V., Ferreiro E., Guedes J., Cardoso A.M.,Cunha P., de Almeida L.P., de Oliveira C.R., de Magalhães J.P.,Peça J., Cardoso A.L. miRNA-31 improves cognition and abolishesamyloid-β pathology by targeting APP and BACE1 in an animalmodel of Alzheimer’s disease." (PMID 38680184, 2024). "BACE1 (β‐secretase) inhibitors for the treatment of Alzheimer's disease." (PMID 39346788, 2024). "Therefore, reducing Aβ through control of BACE-1 activity is a sensible therapeutic goal to treat Alzheimer’s disease." (PMID 37109481, 2023). "Likewise, DL strongly inhibited cholinergic (AChE and BChE) and β-amyloid formation enzymes (BACE-1), thereby showing potential as an effective agent to control Alzheimer’s disease." (PMID 38066118, 2023).
Alzheimer disease (continued). "Since obesity is closely related to T2DM, and Alzheimer’s disease (AD) is also recognized as “type III diabetes,” we checked the expression of genes encoding proteins that are involved in amyloid-beta (Aβ) generation (ADAM10, BACE1, PSEN2, and GSK3β)." (PMID 37432552, 2023). "MiR-9, miR-125b, and miR-128 are expressed in the Alzheimer’s disease brain over the average adult abundance, whereas miR-107 is reduced in early AD and may regulate BACE1 to promote disease progression." (PMID 37038472, 2023). "Thus, the inhibition of the proteolytic activity of BACE1 is interesting for Alzheimer’s disease treatment." (PMID 36964207, 2023). "The inhibition of BACE1 is one of the important therapeutic approaches of Alzheimer’s disease." (PMID 38048081, 2023). "The β-secretase BACE1, which initiates amyloid-β (Aβ) production, is a long-standing prime therapeutic target for Alzheimer's disease (AD) based on solid evidence that Aβ increase is the first event driving subsequent pathological changes and cognitive symptoms." (PMID 39081986, 2023). "Abnormal accumulation of amyloid beta peptide (Aβ) in the brain induces a cascade of pathological changes in Alzheimer’s disease (AD), and inhibiting BACE1, which is required for Aβ generation, is therefore being explored for the treatment of AD by reducing Aβ accumulation." (PMID 37143090, 2023). "Efficient gene silencing of BACE1, a protein involved in Alzheimer’s disease, could be achieved by several groups using polyplex as well as exosome formulations that were functionalized with RVG29." (PMID 36109461, 2023). "Additionally, our study has major implications for the development of BACE1-targeted therapies in Alzheimer’s disease." (PMID 36810097, 2023). "β-secretase 1 (BACE1) is the therapeutic target of Alzheimer’s disease, so developing a DNA aptamer that binds to BACE1 to treat the disease may be an effective measure." (PMID 36910146, 2023). "Alzheimer’s disease (AD) pathogeneses is related to the formation of amyloid plaque generating by degradation of the amyloid precursor protein through the reaction of β-secretase (BACE-1)." (PMID 37050065, 2023). "BACE1-targeted inhibitors have advanced to phase 3 trials for Alzheimer’s disease." (PMID 34958451, 2022). "They found that sarsasapogenin inhibited key enzymes involved in Alzheimer’s disease pathogenesis, including acetylcholinesterase (AChE), butyrylcholinesterase (BuChE), beta-secretase 1 precursor (BACE1), and monoaminoxidase-B (MAO-B) in a concentration-dependent way." (PMID 35335393, 2022). "Another study indicated that bergenin and its analogs have an inhibitory effect on BACE1 and hence may be useful in Alzheimer’s disease." (PMID 36249784, 2022). "The Ng/BACE1 ratio is a predictor for reduced cognition throughout the Alzheimer’s disease continuum and may serve as a biomarker for synaptic dysfunction." (PMID 36262371, 2022). "Interestingly, both ZDHHC20 and ZDHHC21 have a potential role in the pathogenesis of Alzheimer’s disease, as they can palmitoylate BACE1, Tau and amyloid precursor protein." (PMID 35819139, 2022). "In addition, physalin B is effective against Alzheimer’s disease through downregulation of β-amyloid (Aβ) secretion and beta-secretase 1 (BACE1) expression by activating forkhead box O1 (FoxO1) and inhibiting STAT3 phosphorylation." (PMID 35163960, 2022). "Our results demonstrate that voluntary wheel running in an ovariectomized model prevented increases in BACE1 activity, maintained memory recall, and may provide a method of slowing the progression of Alzheimer’s disease." (PMID 36561562, 2022). "If Ng and BACE1 levels are consistent traits, they may point to Alzheimer’s disease subtypes and the need for different treatment strategies." (PMID 36262371, 2022). "Our results suggest that neurogranin and BACE1 levels may differentiate pathomechanistic Alzheimer’s disease subgroups, putatively with different options for treatment." (PMID 36262371, 2022).
Alzheimer disease (continued). "Therefore, BACE1 expression is frequently reported to be upregulated in brain samples of the patients with Alzheimer’s disease (AD)." (PMID 35386116, 2022). "lncRNA BACE1 is used as a potential biomarker for the diagnosis of Alzheimer's disease (AD)." (PMID 33791072, 2021). "Similar findings were reported in other studies that showed greater BACE1 activity in amnestic, mild cognitive-impaired patients compared to Alzheimer’s disease patients and mild cognitive-impaired patients due to Alzheimer’s disease compared to healthy controls." (PMID 33578866, 2021). "The administration of RVG-exosomes containing β-site amyloid precursor protein cleaving enzyme (BACE1) siRNA in wild-type mice significantly reduced mRNA and protein levels of BACE1, a key target for therapeutic inhibition of β-amyloid production in Alzheimer’s disease." (PMID 34831153, 2021). "These compounds exhibited potential abilities in inhibiting BACE1 and acetylcholinesterase (AchE) that might provide a new template for the development of new anti-Alzheimer ́s disease drugs." (PMID 34356949, 2021). "Given the lack of appropriate pharmacological regulation of BACE1, research must focus on understanding the physiological regulation of BACE1 and how diet and exercise may be utilized to prevent Alzheimer’s disease." (PMID 34017238, 2021). "BACE1 is a well-studied enzyme in the field of Alzheimer’s disease." (PMID 33722254, 2021). "In addition to exhibiting AuNP transport across the BBB, the authors note that BACE1 is a potential therapeutic target for Alzheimer’s disease." (PMID 34959296, 2021). "Furthermore, in a mouse model of Alzheimer’s disease, VPS35 heterozygosity worsens Alzheimer’s disease-like Aβ pathology by modulating BACE1 activity." (PMID 34704029, 2021). "In Alzheimer’s disease (AD), two cholinesterases (ChEs) including acetylcholinesterase (AChE) and butyrylcholinesterase (BChE) are neurotransmitter degrading enzymes, while β-secretase (BACE-1) is involved with β-amyloid formation." (PMID 33924574, 2021). "Although these findings raise the possibility that BACE1 inhibitors, developed to treat Alzheimer's disease, could be used to treat T2DM, these inhibitors unfortunately enhanced impairment of cognitive/memory processes in Alzheimer patients." (PMID 34766133, 2021). "Finally, we investigated the CSF ß‐secretase 1 (BACE‐1) as an increase of the protein has been suggested to reflect the intensity of axonal degeneration in adult patients with Alzheimer's disease." (PMID 34312963, 2021). "CSF BACE1 activity and its protein levels could be utilized for the early diagnosis and progression of Alzheimer’s disease." (PMID 33578866, 2021). "Therefore, accelerated long‐term forgetting represents a sensitive paradigm that can detect subtle cognitive decline and help evaluate early BACE1 interventions during presymptomatic stages of Alzheimer's disease." (PMID 33749160, 2021). "Variants in BACE1 and/or γ-secretase substrates, as well as variants in PSEN1, encoding the catalytic domain of γ-secretase, are linked to many pathophysiological conditions, including Alzheimer’s disease, epileptic encephalopathy, cardiac disease, and cancer." (PMID 33411695, 2021). "Several studies on the effects of H. fusiformis extract against Alzheimer’s disease have reported that saponin and glycyrrhizin and its metabolites (18β-glycyrrhetinic acid) inhibited β-site amyloid precursor protein cleaving enzyme 1 (BACE1)." (PMID 34359532, 2021). "Similarly, BACE1 activity and protein concentration were significantly increased in Alzheimer’s disease patients compared to elderly healthy controls." (PMID 33578866, 2021). "Examples of DRL-based de novo drug design include the development of adenosine A2A receptor ligands, rapid identification of potent DDR1 kinase inhibitors, and the development of a large number of new BACE1 inhibitors, which is an enzyme involved in Alzheimer’s disease." (PMID 33562347, 2021).
Alzheimer disease (continued). "BACE1 gene encodes an enzyme that cuts the amyloid precursor protein (APP) and produces amyloid beta peptides that cause amyloid plaque in the brains of patients with Alzheimer’s disease." (PMID 34306005, 2021). "In the study, melatonin had further injury-reducing effects through decreased apoptotic cell death and lesion volume and a significant reduction in levels of expression of the Alzheimer’s disease marker proteins beta-site amyloid precursor protein cleaving enzyme 1 (BACE-1), APP, and Aβ proteins." (PMID 34659987, 2021). "Similarly, in a case–control and longitudinal follow-up study, higher BACE1 activity was found in subjects with mild cognitive impairment who developed Alzheimer’s disease compared to persons with mild cognitive impairment who remained stable." (PMID 33578866, 2021). "Additionally, the overproduction of CSF BACE1 protein concentrations by stressed glial or neurons decreases during the progression to Alzheimer’s disease, reflecting accelerated brain atrophy." (PMID 33578866, 2021). "β-site APP-cleaving enzyme 2 (BACE2), the homolog of BACE1, might play a complex role in the pathogenesis of Alzheimer’s disease as it is not only a θ-secretase but also a conditional β-secretase." (PMID 32160867, 2020). "In addition, the group further developed a bispecific therapeutic antibody with a low affinity for TfR and a high affinity for another Alzheimer’s disease drug target, the BACE1." (PMID 31940974, 2020). "For example, 1 is reported to exhibit inhibitory activity towards both acetylcholinesterase (AChE) and β-secretase (BACE-1), which suggests that 1 could hold promise as a dual mechanism-of-action treatment for Alzheimer’s disease." (PMID 33178356, 2020). "BACE-1 is a membrane-anchored aspartic acid protease and is responsible for the production of amyloid beta peptides in neurons related to the progression of Alzheimer’s disease." (PMID 33050240, 2020). "Dysregulation of this pair of miRNA and lncRNA, both found over-expressed in different regions of AD brain tissues, may induce the up-regulation of BACE1 and consequently the onset of Alzheimer’s disease." (PMID 32605220, 2020). "Astrocytes may not only be involved in the clearance of Amyloid beta peptides (Aβ) in Alzheimer's disease (AD), but appear to produce N-terminally truncated Aβ (Aβn−x) independently of BACE1, which generates the N-Terminus of Aβ starting with Asp1 (Aβ1−x)." (PMID 33510618, 2020). "Beta-secretase 1 (beta-site amyloid precursor protein (APP)–cleaving enzyme 1; BACE1) enzymatic activity is implicated in the pathophysiology of brain amyloid-beta (Aβ) accumulation in Alzheimer’s disease (AD)." (PMID 32140803, 2020). "The therapeutic potential of BACE1 silencing has been proposed several times due to its direct association with neurodegeneration and accumulation of APP products during early stages of Alzheimer’s disease." (PMID 32515999, 2020). "Acetylcholinesterase (AChE) and beta-secretase (BACE-1) are two attractive targets in the discovery of novel substances that could control multiple aspects of Alzheimer’s disease (AD)." (PMID 32867308, 2020). "BACE1 has been well characterized in the pathogenesis of Alzheimer’s disease, since it is one of the main enzymes responsible for the processing of the amyloid precursor protein and for the generation of amyloid beta plaques, a pathological hallmark of the disease." (PMID 30949030, 2019). "Targeting BACE1 has been a strategy for treating Alzheimer’s disease." (PMID 31816964, 2019). "β-Site APP-cleaving enzyme 1 (BACE1) inhibition to treat Alzheimer’s disease also inhibits BACE2." (PMID 30456346, 2018). "Also, eNOS-/- mice had increased amyloid precursor protein (APP), β-site APP-cleaving enzyme 1 (BACE1), and β-amyloid peptide (Aβ) in their brains compared to those of wild-type mice, which contribute to the pathogenesis of Alzheimer’s disease (AD)." (PMID 29896421, 2018).
Alzheimer disease (continued). "BACE1 is the rate-limiting protease in the production of synaptotoxic β-amyloid (Aβ) species and hence one of the prime drug targets for potential therapy of Alzheimer’s disease (AD)." (PMID 29327084, 2018). "There is some data indicating that BACE1 increase in Alzheimer’s disease might be a result of translational derepression of the BACE1 mRNA 5′-UTR induced by energy metabolism stress." (PMID 29065505, 2017). "Inhibition of BACE1 proteolytic activity has been confirmed to decrease Aβ generation and amyloid deposition, and thus specific inhibition of BACE1 by small molecules is a current focus for Alzheimer’s disease therapy." (PMID 28469554, 2017). "BACE1 is a crucial protease in the pathogenesis of Alzheimer’s disease." (PMID 28091531, 2017). "BACE1 concentration increase is typical for Alzheimer’s disease." (PMID 29065505, 2017). "Furthermore, compounds 3, 13 and 16 exhibited promising application in the treatment of Alzheimer's disease owing to their good inhibitory activities against BACE1." (PMID 28791165, 2017). "Similarly, miR-135b was demonstrated to exert a neuroprotective role via direct targeting of β-site APP-cleaving enzyme 1 (BACE1) in Alzheimer's disease (AD)." (PMID 28484287, 2017). "For the past 17 years, extensive efforts have been focused on the development of compounds that specifically inhibit BACE1 activity for Alzheimer’s disease (AD) therapy, and several major hurdles of producing brain-penetrable small molecular inhibitors have been overcome." (PMID 28469554, 2017). "Similarly, the administration of competitive inhibitors of BACE1 improves outcomes in animal models of Alzheimer’s disease and provides the rationale for extending this treatment to patients." (PMID 27456313, 2016). "Many key proteins involved in disease progression are N-glycosylated, such as amyloid precursor protein (APP) and β-site amyloid precursor protein-cleaving enzyme 1 (BACE-1) in Alzheimer's disease (AD) and alpha-fetoprotein (a clinical biomarker) in hepatocellular carcinoma." (PMID 27259237, 2016). "For this reason, we investigated the efficacies of taxifolin alone and in combination with cilostazol with respect to the regulation of BACE1, Aβ accumulation, and the inhibition of neuroinflammation with a view towards possible intervention in Alzheimer’s disease." (PMID 27977755, 2016). "The protease BACE1 (beta-site APP cleaving enzyme) is a major drug target in Alzheimer’s disease." (PMID 27716410, 2016). "In addition, APLP1 is one of the substrates of BACE1, an enzyme involved in Alzheimer’s disease pathology." (PMID 27186164, 2016). "Golgi-localized γ-ear-containing ARF binding protein 3 (GGA3) is a monomeric clathrin adaptor that has been shown to regulate the trafficking of the Beta-site APP-cleaving enzyme (BACE1), which is required for production of the Alzheimer’s disease (AD)-associated amyloid βpeptide." (PMID 27192432, 2016). "Therefore, as it catalyzes the initial site-specific hydrolysis step of Aβ production, BACE-1 is an attractive therapeutic target for the treatment of Alzheimer’s disease." (PMID 26506513, 2015). "The first two documents, both published on May 1st 2014, were WO2014066132 from Eli Lilley and WO2014065434 from Shionogi, both specifying BACE1 inhibitors for Alzheimer's disease (6132 used BACE as a synonym for BACE1, UniProt P56817)." (PMID 26194581, 2015). "Our findings indicate that reduction in amyloid-β via inhibition of BACE-1 may have the desired beneficial downstream effects on Alzheimer’s disease pathology." (PMID 26336937, 2015). "Therefore, the search for novel BACE-1 inhibitors as potential therapeutics for Alzheimer’s disease (AD) has been undertaken by many scientists from both academia and the pharmaceutical companies." (PMID 24663084, 2014). "Finally, contactin-2 levels were decreased in Alzheimer’s disease brain samples correlating inversely with elevated BACE1 levels in the same samples." (PMID 24405708, 2014).